CXCL13 (C-X-C motif chemokine ligand 13)
Diseases named in the same sentence as CXCL13 in open-access papers (continued):
Sharing a sentence is not in itself a finding about the gene and the disease.
tumor (continued). "Mutation-associated neoantigen (MANA) -specific CD8+ tumor-infiltrating lymphocytes (TIL) have been shown to express high levels of CXCL13 and CD39 (ENTPD1), and low IL-7 receptor (IL7R) levels in many cancer types, but their collective relevance to T cell functionality has not been established." (PMID 39900903, 2025). "TLS gene signatures and CXCL13 expression may serve as independent biomarkers for immunotherapy response and prognosis, outperforming other immune signatures and tumor mutational burden (TMB) in predictive value." (PMID 41457151, 2025). "The immune system may struggle to inhibit tumor growth, yet the presence of T follicular helper cells that produce CXCL13 is linked to organized immune structures near the tumor site." (PMID 40027134, 2025). "Additionally, since CXCL13 is a gene encoding a soluble secreted protein, we posit that it holds potential for use as a serum tumor marker." (PMID 39344390, 2024). "Compared to Mo detected in normal brains, Mo detected in PDOXs showed higher expression levels of genes associated with pro-tumorigenic TAMs (e.g., Cxcl13, Ctsd, Ccl4, Apoe) as well as Mg mimicry (e.g., Spp1, Trem2, Cst7, Tyrobp), further confirming an active crosstalk with tumor cells." (PMID 38566128, 2024). "Tumor-associated fibroblasts had CXCL13 in response to hypoxia and tissue injury." (PMID 38333212, 2024). "The expression of CXCL13 in baseline tumor tissues, along with an ARID1A mutation in tumor cells, has been identified as a predictor of successful clinical responses in metastatic urothelial carcinoma patients treated with nivolumab, an immune checkpoint therapy, through whole-exome sequencing." (PMID 39409924, 2024). "Furthermore, there are some tumor types in which CXCL13 expression is associated with a favorable prognosis for the patient and others in which CXCL13 expression is associated with a poor prognosis." (PMID 37788648, 2024). "Similarly, CXCL11, CXCL12, and CXCL13 encoded the C-X-C motif chemokine ligands, critical regulators of tumor progression in many cancers." (PMID 37537613, 2023). "Additionally, CXCL13 associates with a diverse range of immune cells, reflecting its extensive impact on tumor-associated immune responses." (PMID 37980450, 2023). "Hence, the underlying mechanism which triggers high CXCL13 expression by the tumor microenvironment and how it effects the response to ICI should be carefully interpreted." (PMID 36453453, 2023). "Because several studies have linked CXCL13 expression and a dysfunctional state to tumor reactivity, we hypothesized that C3 contains tumor-specific CD8+ T cells." (PMID 37217652, 2023). "In addition, CXCL13 has been shown to increase B cell and T cell infiltration in multiple tumor types and associate with greater prognosis and survival." (PMID 37875600, 2023). "Interestingly, we also found that the abnormal expression of CXCL9, CXCL11, and CXCL13 is significantly associated to tumor stage, indicating that these CXCLs are closely related to tumor invasion and metastasis." (PMID 36798787, 2023). "The CXCL13/CXCR5 axis is associated with tumor development, proliferation, and invasion." (PMID 37503314, 2023). "High expression of CXCL13 in CD8+ T cells may promote lymphocyte chemotaxis across high endothelial venule into tumor lesions to support TLS formation and was associated with ICIs therapy response." (PMID 35831283, 2022). "Besides these scores, the XP genes, immune-specific single genes (CD8A, CXCL9, CD274, and CXCL13) and tumor mutational burden (TMB) were cross-correlated." (PMID 35174087, 2022). "The CXCL13/CXCR5 axis is linked with tumor development, progression, proliferation, and invasion." (PMID 35053457, 2022). "Taken together, drebrin+ T cells co-expressed multiple exhaustion-associated molecules, including PD-1, TIM-3, LAG-3, and CXCL13, and drebrin was selectively expressed in exhausted tumor-infiltrating CD8+ T cells, suggesting that drebrin is a novel exhaustion-associated molecule." (PMID 36430217, 2022).
tumor (continued). "High CXCL13 levels in gastric tumors are associated with larger tumor diameters." (PMID 31354634, 2019). "CXCL13 gene expression correlated with TLS presence.CXCL13-producing CD4+ T cells are involved in the early stage of TLS formation.TLS formation was associated with CXCL13-producing CD4+ T cells & TLS facilitated the coordinated anti-tumor response of cellular & humoral immunity in OC." (PMID 40475770, 2025). "CXCL13 colocalizing with TLSs shapes anti-tumor microenvironment by maintenance of CXCR5+CD8+ T cells in TLS.TLS prognostic benefit is only relevant in the presence of CXCL13.High CXCL13 expression associated with prolonged survival.Supports a new CXCL13 & PD-1 blockade clinical trial in HGSOC." (PMID 40475770, 2025). "In addition, another study showed that CXCL13 was a B cell chemoattractant and was associated with the formation of tertiary lymphoid structures (TLSs), the ectopic lymphoid tissues that form around tumors and participate in anti-tumor immune responses." (PMID 38066642, 2023). "Additionally, tumor-associated FDCs express CXCL13, which effectively recruits lymphocytes." (PMID 37342327, 2023). "In recent years, CXCL13 has also been found to be closely associated with tumorigenesis and may directly or indirectly modulate the migration and proliferation of tumor cells, influence tumor development and prognosis, and be a potential target for cancer treatment." (PMID 35141160, 2022). "In contrast, most features associated with 4T1 tumour growth were significantly different from normal levels in Nil animals, with G-CSF level and neutrophil count being >10-fold higher, PD-L1+ myeloid cell count being ~2-fold higher, and both CXCL13 and IL-6 levels being ~<2-fold higher than normal." (PMID 35226704, 2022). "In the context of neoadjuvant chemotherapy, the expression levels of multiple immune-related genes including CXCL13 constitute positive prognostic factors for pCR, and it has been demonstrated to be associated with improved disease-free and overall survival after tumor resection." (PMID 35911770, 2022). "In addition to immunosuppressive properties, CXCL13-expressing macrophages in the MM tumor microenvironment may be implicated in chemoresistance." (PMID 36217194, 2022). "Moreover, the formation of tertiary lymphoid structures within tumors could be supported by CXCL13 produced from Tph cells, suggesting an important prognostic factor associated with tumor progression and recurrence." (PMID 35742914, 2022). "To date, research on CXCL13 in cancers has been limited to a specific type of cancer, so it is necessary to perform a pan-cancer analysis on the target gene to evaluate its interrelationship with underlying molecular mechanisms, clinical phenotypic characteristics and tumor immune microenvironment." (PMID 35141160, 2022). "Furthermore, CXCL13 was positively associated with tumor stage and tumor grade." (PMID 32669964, 2020). "In vivo, tumor-derived CXCL13 suppressed tumor growth, increased intratumoral CD8+ T cell infiltration, and enriched CXCR5+TCF1+CD8+ stem-like T cells." (PMID 42146336, 2026). "This review compiles current knowledge on the significance of lesser-known chemokines in MM tumor processes, including CXCL13, CCR2 ligands (CCL2 [MCP-1], CCL7 [MCP-3]), CCL4, CCL5 (RANTES), CCL17, CCL20, CCL27, CCL28, and CX3CL1 (fractalkine)." (PMID 41749925, 2026). "These cells represented a relatively small proportion of the total T cell pool, and showed expression of ITGAE (encoding CD103), CXCL13, ENTDP1, PDCD1 and other checkpoint molecules consistent with previous antigen exposure and tumour reactivity." (PMID 41115454, 2025). "CXCL13 in the TME can attract tumor-specific T cells, promoting their activation and proliferation to enhance immune responses." (PMID 40764989, 2025).
tumor (continued). "These nominated clusters upregulated key marker genes of activation, dysfunction, and differentiation that have been used to identify tumor specificity, such as CXCL13, TIGIT, PDCD1 (PD1), ENTPD1 (CD39), TOX, HAVCR2 (TIM-3), and LAG3." (PMID 40848148, 2025). "Previous studies have shown that the CXCL13/CXCR5 axis contributes to tumor growth, proliferation, metastasis, and invasion." (PMID 40649942, 2025). "CXCL13, in combination with anti-PD-1 therapy, retarded tumor growth in vivo, resulting in increased infiltration of CXCR5+CD8+ T cells." (PMID 40406143, 2025). "These CAR T-cells exhibited enhanced migration toward CXCL13-positive targets and improved in vivo anti-tumor activity." (PMID 41019052, 2025). "The treatment response to CXCL13 and anti-PD-1 antibody was investigated using a subcutaneous xenograft tumor mouse model." (PMID 40406143, 2025). "Clonal expansion, representing the generation of tumor‐reactive T cells, suggests that CXCL13 and ITGAE are potential markers for tumor‐reactive T cells in MIBC." (PMID 39739621, 2025). "The observation that exhausted or dysfunctional CD8+ and CD4+ T cells within tumors frequently express the B‐cell‐attracting chemokine CXCL13 suggests a programmed mechanism through which T cells recruit B‐cell support in response to persistent tumor antigens." (PMID 41235705, 2025). "Spatial transcriptomics corroborates these insights, mapping PD-L1-high tumour islets millimetres from CXCL13-rich tertiary lymphoid structures, whereas CITE-seq quantifies actionable checkpoints and cytokine receptors across patient biopsies." (PMID 40959084, 2025). "The relative RNA expression demonstrated that Ccl5, Ccl8, Cxcl9, Cxcl10, Cxcl13 and Ccl21 were significantly higher in the 4MOSC1 tumours following oHSV therapy." (PMID 39219056, 2025). "In pre-NAIC tumor tissue, the proportions of CD4_Tfh_CXCL13 cells in MPR patients were higher than that in NMPR patients." (PMID 40295492, 2025). "The results demonstrated a significant positive correlation between CXCL13 expression levels and TLS presence (r = 0.7126, p < 0.001), providing strong theoretical support for further investigation into the role of CXCL13 in the tumor immune microenvironment." (PMID 40352278, 2025). "Explainable AI then identified the top 10 transcripts whose abundance was predictive of tumour-reactive T cells including CXCL13, ANXA1, IL-7R, and TPT1, although the broad applicability of this approach in diverse cancer types still needs to be explored." (PMID 40801654, 2025). "They demonstrated that CAR T-cells armored with LIGHT upregulated expression of chemokines CCL19, CCL21, and CXCL13 in both stromal cells and tumor cells, enhancing the ability of the stromal cells to recruit T-cells in migration assays." (PMID 41019052, 2025). "CXCL13 has been reported to regulate tumor development, and patients with high CXCL13 levels exhibit poor outcomes." (PMID 40325003, 2025). "Next, we examined the expression patterns of the 14 selected candidate genes and observed that only TNFRSF18 and CXCL13 were specifically expressed in tumour tissues and exhausted CD8+ T cells." (PMID 40770837, 2025). "CXCL13 CAR T cells exhibited enhanced tumor‐killing capacity relative to control cells, an effect that was substantially diminished by either inhibitor." (PMID 40492496, 2025). "This suggests that the overrepresentation of Treg/Tfh CD4 T cells in the tumor, was in part due to the increased proportion of CXCL13+Tfh cells." (PMID 39932553, 2025). "Compared to CXCL13‐ T cells, CXCL13+ T cells expressed more tumor‐reactive markers and exhibited significant clonal expansion." (PMID 39739621, 2025). "While CXCL13 is known to be correlated with the immunosuppressive status of a variety of tumours,58, 59, 60, 61TNFRSF18 represents a novel validated marker." (PMID 40770837, 2025).
tumor (continued). "For instance, higher levels of CXCL13, a cytokine correlated to T-cell tumor specificity, has been reported in T cells isolated from female compared to male patients." (PMID 40589738, 2025). "The expression level of CXCL13 was prominently higher in MPR_Pre-NAIC_Tumor group, especially in CD4_Tfh_CXCL13 cells subtype." (PMID 40295492, 2025). "In vitro co‐culture assays with tumor cells demonstrated that CXCL13 CAR T cells had significantly greater tumor‐killing efficacy compared to control CAR T cells." (PMID 40492496, 2025). "Specifically, the expression of TNFRSF18 gradually decreased with the advancing stage, whereas the expression of CXCL13 increased, suggesting they have a significant impact on T cell function and anti‐tumour immunity." (PMID 40770837, 2025). "TCGA cohort confirmed that CXCL13 influences cell survival and is closely correlated with CD8Teff activity, reinforcing its role as a key modulator in the tumor microenvironment." (PMID 40971094, 2025). "When CXCL13 secreting T cells infiltrate a tumour they can attract B cells expressing the CXCR5 receptor and cause aggregates of B cells to form, therefore inducing the formation of a TLS." (PMID 39462771, 2025). "In initial in vitro co‐culture assays, CXCL13 CAR T cells demonstrated superior tumor‐killing efficacy compared to control CAR T cells." (PMID 40492496, 2025). "The data above demonstrated that CXCL13‐expressing CAR T cells possess multiple characteristics to facilitate their tumor immunotherapeutic efficacy." (PMID 40492496, 2025). "CXCL13 expression was significantly reduced in tumours with high ACLY expression and increased in those with low expression, mirroring mouse data." (PMID 40739358, 2025). "Emerging observations reported that CXCL13 can modulate tumor progression, such as the tumor-specific immune response, angiogenesis and metastasis." (PMID 40943634, 2025). "Posttreatment alterations included a significant increase in CXCL9+ cells and CXCL13 + T cells, particularly around tumour cells." (PMID 40670667, 2025). "By using Xenium Explorer, we confirmed strong expression of CXCL9 and CXCL13 in almost all areas around the tumour, including at sites of tumour eradication." (PMID 40670667, 2025). "Those anti-tumor effects are mainly caused by the pathways of B cells, such as CCL19, -21/CCR7 axis and CXCL13/CXCR5 axis." (PMID 40158161, 2025). "Combination treatment with CXCL13 and anti-PD-1 antibody significantly suppressed tumor growth compared to both the monotherapy and control groups." (PMID 40406143, 2025). "In the MPR_Pre-NAIC_Tumor and MPR_Post-NAIC_Tumor groups, CD4+ T cells were enriched with the CXCL13 signaling pathway and T cell-induced cell death process, whereas the Tregs differentiation process was weakly enriched in the MPR_Post-NAIC_Tumor." (PMID 40295492, 2025). "Pafs were subclassified into inflammatory Pafs, myofibroblastic Pafs (myPafs) and a small population named tumor immunity- and angiogenesis-promoting Pafs (tapPafs), expressing Cxcl13." (PMID 40548381, 2025). "Pre-NAIC, the effector T cell (CD4_Tact, CD4_CTL, CD8_Teff, CD8_Tact and CD4_Tfh_CXCL13, etc) were more prevalent in tumor tissue than in paracarcinoma tissue." (PMID 40295492, 2025). "This discrepancy is likely due to reduced tumor necrosis and higher viable cell density in the CXCL13 group, resulting in increased absolute CAR T cell numbers without a corresponding change in their proportional representation among live cells." (PMID 40492496, 2025). "Clonal expansion was predominantly restricted to the CXCL13+ Tex subset, confirming this subtype as tumor reactive." (PMID 41045934, 2025). "Previous studies have demonstrated that CXCL13+ T cells exhibit an exhausted phenotype characterized by elevated exhaustion markers and reduced effector cytokine production, yet retain strong tumor-reactive capacity." (PMID 40883281, 2025).
tumor (continued). "Elevated CXCL13 levels are linked to an increased presence of TLS and lower histopathological grades, indicating a more organized and potentially less aggressive tumor microenvironment." (PMID 40352278, 2025). "Higher clonal ratio was mainly observed in CD4_Tfh_CXCL13 and CD8_Teff cells for MPR_Pre-NAIC_Tumor samples." (PMID 40295492, 2025). "To further enrich for tumor-reactive candidates, we next examined the expression of CXCL13 and the NeoTCR8 score, a transcriptomic signature of neoantigen-reactive CD8+ T cells." (PMID 41294842, 2025). "The authors also found that treatment with ibrutinib disrupts the interaction between tumor-associated macrophages (TAM) and tumor cells in the bone marrow, inhibits the secretion of CXCL13, and decreases the chemoattraction of CLL cells." (PMID 40864758, 2025). "Activated CD103+ cytotoxic T lymphocytes (CTLs) play a crucial role in the recruitment of B cells to the tumor microenvironment through the secretion of CXCL13." (PMID 39926286, 2025). "The metastatic group was characterized predominantly by an exhausted subcluster (CD8_Tex_CXCL13), implying that most tumor-infiltrating T cells in metastatic group are depleted and damaged due to long-term chronic antigen stimulation." (PMID 40657372, 2025). "Proliferative CXCL13+ CTLs were enriched in Domain A, which also contained the highest density of proliferating tumor cells." (PMID 41473281, 2025). "Significant cytokine variations were detected between these groups, with CXCL13 emerging as a critical cytokine that potentially affects multiple pathways in tumor microenvironment." (PMID 40971094, 2025). "Analysis of these signature genes showed an overall upregulation trend in tumor tissue, with CXCL13 exhibiting significantly higher expression in tumor compared to normal tissues." (PMID 40464813, 2025). "As confirmed in Patient 7, upregulation of CXCL9+ and CXCL13+ cells and localization within the tumour were confirmed in all post anti-PD-L1-CRT tissues." (PMID 40670667, 2025). "Our initial focus was on understanding the mechanisms through which CXCL9+ cells and CXCL13+ cells are attracted to the tumour vicinity and evaluating chemokines, interleukins, and IFN receptors." (PMID 40670667, 2025). "Spatial interaction analysis demonstrated CXCL10+ M2 macrophage-derived chemotactic gradients at tumor–stroma interfaces and CXCL13/CCL19 chemokine gradients within B-T cell co-localization regions." (PMID 40867511, 2025). "CXCL13+ cancer-associated fibroblasts (CAFs) enhance B cell adhesion and antibody production, while activating exhausted CXCL13+CD8+ T cells in tumor cell aggregates." (PMID 41285707, 2025). "Of those genes which are differentially expressed in MANA-specific TIL vs EBV-/flu-specific TIL, CXCL13 emerged as an effective marker for identifying tumor-reactive T cells within the TME10." (PMID 39900903, 2025). "Studies have shown that IL-1β of TME promotes tumor progression through increasing CXCL13 expression and infiltration of immune-suppressive IL-35+ B cells." (PMID 39744696, 2025). "We observed that responders had a significantly lower CXCL13+ cell density in the tumor (p = 0.016), even considering the surrounding area of the tumor (CXCL13+ (T+IM), p = 0.019; or CXCL13+ (T+IM+NT), p = 0.003; or CXCL13+ cells (T+NT), p = 1.5 × 10−3)." (PMID 38398098, 2024). "The relationship between CXCL13 and immunity was further studied and CXCL13 was positively correlated with infiltrating immune cells, which means a close relationship between CXCL13 and anti-tumor immunity." (PMID 38459390, 2024). "CXCL13 correlates with elevated T follicular helper cells and innate cells in the tumor microenvironment, binding to CXCR5 on the cell membrane." (PMID 38844562, 2024). "In solid tumors, the tumor-reactive T cells are characterized by high expression levels of CXCL13 or exhaustion signatures." (PMID 39243082, 2024).